SPP1 (secreted phosphoprotein 1)
Diseases named in the same sentence as SPP1 in open-access papers (continued):
Sharing a sentence is not in itself a finding about the gene and the disease.
cervical carcinoma (continued). "SPP1 was found to be related to the age and histology of cervical cancer patients." (PMID 32300605, 2020). "Upregulation of SPP1 has been reported in expression profiling studies of cervical cancer as well." (PMID 24403257, 2013). "In this study, SPP1 may play an important role in the development of cervical cancer." (PMID 35154316, 2022). "In our research, we utilized the cervical cancer RNA-seq data from The Cancer Genome Atlas (TCGA), Gene Expression Omnibus (GEO), and Genotype-Tissue Expression databases to compare the differential expression of SPP1 between normal cervical tissues and cervical cancer samples." (PMID 35058964, 2021). "We believe that the combination of bulk RNA-seq and single-cell sequencing data will help us confirm the gene signatures of C1QC+ and SPP1+ TAMs in the cervical cancer microenvironment and signaling pathways, which may activate or in-activate in different TAMs subsets." (PMID 34295336, 2021). "Furthermore, we explored the prognostic value of SPP1 in cervical cancer." (PMID 35058964, 2021). "Therefore, we hypothesised that SPP1 might contribute to tumour aggressiveness and influence cervical cancer prognosis by regulating M2 macrophages, but this hypothesis requires further investigation and validation." (PMID 34498424, 2021). "In addition to this, SPP1 might participate in the occurrence and development of cervical cancer by influencing the infiltration level of immune cells." (PMID 35058964, 2021). "C1QC+ and SPP1+ TAMs gene signatures were obtained from TAMs; however, they could significantly divide patients into subgroups with distinct clinical outcomes, implying the importance of TAMs in the development of cervical cancer." (PMID 34295336, 2021). "We compare the C1QC+ and SPP1+ TAMs gene signatures with the M1/M2 gene signatures at single cell level and bulk RNA-seq level and evaluate which gene signature can clearly divide TAMs and patients with cervical cancer into distinct clinical subclusters better." (PMID 34295336, 2021). "Immunohistochemistry results further verified the high expression of SPP1, LYZ, and MCM5 in patients with RA combined with cervical cancer." (PMID 41384115, 2025). "Current research on cervical cancer has revealed distinct functional roles of CXCL9 and secreted SPP1 in tumor pathogenesis." (PMID 40936719, 2025). "This study successfully identified SPP1, LYZ, and MCM5 as key hub genes for the comorbidity of RA and cervical cancer." (PMID 41384115, 2025). "On this basis, we successfully identified three hub genes (SPP1, LYZ, and MCM5) that were differentially expressed in the prognosis of RA and cervical cancer." (PMID 41384115, 2025). "Combining SPP1 and CD44 can serve as an early biomarker for cervical cancer diagnosis and prognosis." (PMID 38346944, 2024). "The candidate genes SPP1, FOXM1, LYN, COL6A3, CCL21, TTK and MELK at mRNA level, emerge as promising candidate markers for cervical cancer prognosis and also emerge as potential therapeutic drug targets." (PMID 33829064, 2021). "Thus, SPP1 may become a promising prognostic biomarker for cervical cancer patients." (PMID 35058964, 2021). "The prognostic values of SPP1, EFNA1, and MMP-1 in cervical cancer have been investigated in previous studies." (PMID 32300605, 2020). "Next, we evaluated the three genes’ potential for diagnosis, SPP1, LYZ, and MCM5, in the RA test set data (GSE55235, GSE55457, and GSE77298) and validation set (GSE89408) as well as the cervical cancer test data sets (TCGA and GTEx) and validation set (GSE63514)." (PMID 41384115, 2025). "Second, cervical cancer subgroups divided by C1QC+ and SPP1+ TAMs gene signatures showed different immune cell infiltration, with the C1QChigh and SPP1low groups have the highest immune cell infiltration, whereas the C1QClow and SPP1high groups had the lowest immune cell infiltration." (PMID 34295336, 2021).
cervical carcinoma (continued). "However, whether TAMs in cervical cancer show as the M1 and M2 phenotypes or C1QC+ and SPP1+ TAMs phenotypes remains unknown." (PMID 34295336, 2021).
osteosarcoma (50 papers, 2006 to 2026). A usually aggressive malignant bone-forming mesenchymal neoplasm, predominantly affecting adolescents and young adults. "Specifically, we observed that chemotherapy resulted in a subpopulation of osteosarcoma (OS) cells with upregulated expression of genes encoding secreted factors, such as SPP1 and LUM, as well as a distinct population of malignant OS cells." (PMID 39033089, 2024). "M2 macrophages communicated with osteoblasts by the APP, MIF, and SPP1 signaling pathways, facilitating osteosarcoma development." (PMID 40092698, 2025). "M2 macrophages communicated with osteoblastic cells via the APP, MIF, and SPP1 signaling pathways, facilitating osteosarcoma development." (PMID 40092698, 2025). "qRT-PCR showed MYC, BNIP3, IGFBP5, and SPP1 substantially exhibited a trend of high expression in osteosarcoma cells." (PMID 41282023, 2025). "On the other hand, ESRRA also exerts repression effect on SPP1 promoter transactivation in human osteosarcoma cell lines SaOs-2 and U2-OS by cross-talking with another nuclear receptor NR4A258." (PMID 38704393, 2024). "A recent study demonstrated that S100A4 induces NF-κB-dependent expressions and secretions of SPP1 in osteosarcoma cell lines." (PMID 35721061, 2022). "SPP1 is now of interest in carcinogenesis, Lysosomal-associated membrane protein 3 (LAMP3) enhances osteosarcoma cell invasion via SPP1 signaling." (PMID 36303551, 2022). "Antisense knockdown of SPP1 RNA in osteosarcoma cells results in inhibition of in vivo tumorigenesis in mice." (PMID 20465837, 2010). "THBS3, SPARC and SPP1 were identified by cDNA array as genes differentially expressed in osteosarcoma." (PMID 17022822, 2006). "Overexpression of SPP1 was found in 47 of 53 (89%) osteosarcomas correlating with better overall survival, event-free survival and relapse free survival at diagnosis." (PMID 17022822, 2006). "In summary, although SPP1 is not essential for the development of osteosarcoma, further research is necessary to elucidate its underlying mechanisms." (PMID 41391064, 2025). "Surprisingly, all these osteosarcoma cell lines exhibited SPP1 expression." (PMID 39033089, 2024). "Notably, we analyzed SPP1 protein levels in several osteosarcoma cell lines, including 143B, MNNG, U2OS, HOS, SAOS2, and MG63." (PMID 39033089, 2024). "However, some scholars found that overexpression of SPP1 was correlated with improved overall survival, event-free survival, and relapse-free survival at diagnosis in osteosarcoma." (PMID 36303551, 2022). "THBS3, SPARC and SPP1 were identified as genes differentially expressed in osteosarcoma." (PMID 17022822, 2006). "Given the documented chemotherapy resistance in osteosarcoma, our findings suggested that chemotherapy could intensify its malignancy.One of our most compelling findings revolves around the increased expression of SPP1 in post-chemotherapy osteosarcoma cells." (PMID 39033089, 2024). "SPP1 is not necessary for tumor progression in osteosarcoma and may be associated with inflammatory response and bone remodeling, functioning as a good biomarker." (PMID 17022822, 2006). "We examined SPP1 expression in osteosarcoma cells, with MCF7 serving as a negative control and MB231 serving as a positive control for SPP1 expression, as previously reported." (PMID 39033089, 2024). "Moreover, increased SPP1 was found to upregulate p‐STAT3, which activated STAT3 signalling in osteosarcoma and rat hepatocytes." (PMID 35184394, 2022).
osteosarcoma (continued). "SPP1, VEGFA, EMMPRIN, MIF, uPAR, Angiogenin, and Cystatin C were among the most highly expressed analytes in both patient specimens and in cell line conditioned media, demonstrating that the osteosarcoma cells themselves are a cellular source of these molecules." (PMID 39896512, 2025). "The SPP1, FGF, and NOTCH signaling pathways may play a crucial role in osteosarcoma TME regulation." (PMID 36303551, 2022).
osteoarthritis (49 papers, 2011 to 2025). A noninflammatory degenerative joint disease occurring chiefly in older persons, characterized by degeneration of the articular cartilage, hypertrophy of bone at the margins and changes in the synovial membrane. "Many studies have found higher levels of SPP1 in the plasma and synovial fluid of patients with osteoarthritis than in healthy adults, indicating that SPP1 may be associated with the severity of osteoarthropathy." (PMID 41357134, 2025). "The association between SPP1 and osteoarthritis has been demonstrated." (PMID 27146865, 2016). "SPP1-deficient mice exhibit accelerated development of osteoarthritis." (PMID 27146865, 2016). "We look forward to subsequent researchers conducting more in vivo studies to provide more evidence that SPP1 affects osteoarthritis through ECM dynamics." (PMID 41293726, 2025). "Future work should prioritize in vivo validation in osteoarthritis and clinical translation of SPP1-directed therapies." (PMID 41293726, 2025). "Unfortunately, most studies on the role of SPP1 in osteoarthritis are based on bioinformatics analysis, with few in vivo experiments." (PMID 41293726, 2025). "Future research should concentrate on verifying these pathways in vivo, particularly in osteoarthritis, and enhancing the therapeutic use of SPP1-targeted medicines." (PMID 41293726, 2025). "Through the study of related literature, we found that miR-186 inhibits osteoarthritis chondrocyte apoptosis by interacting with SPP1 and regulating the Phosphatidylinositol‐ 3 kinase (PI3K)/protein kinase B (Akt) pathway." (PMID 31485443, 2019). "However, Spp1 has been reported to alleviate the progression of osteoarthritis via Cd44 when injected into knee joints." (PMID 39563425, 2024). "Past evidence showed the linkage between tissue bone bridging protein (SPP1) and osteoarthritis." (PMID 35734177, 2022). "The authors’ study identified leucine rich repeat containing 15 (LRRC15) and secreted phosphoprotein 1 (SPP1) as hub genes in calcific aortic valve disease (CAVD) and osteoarthritis (OA) and found that they were related to immune processes." (PMID 38566328, 2024). "The analysis revealed a notable upregulation of key osteoarthritis markers, such as COL10A1, MMP13, and SPP1, along with downregulating chondrogenic markers, including ACAN, COL1A2, COL2A1, and SOX9." (PMID 39337501, 2024). "RNA sequencing unveiled significant transcriptome changes during the 7-day SMG culture, including the notable upregulation of key osteoarthritis markers such as COL10A1, MMP13, and SPP1, along with pathways related to inflammation and calcification." (PMID 38907358, 2024). "The cellular communication among chondrocyte subtypes mediated by signaling pathways, such as PTN, VISFATIN, SPP1, and TGF-β, was selectively altered in Osteoarthritis." (PMID 37082621, 2023). "OPN/SPP1 is overexpressed in the cartilage and synovium of osteoarthritis patients with osteoarthritis." (PMID 36522666, 2022). "Microarray analysis data of ARV infected cells and σB transfected cells were validated by using primers of 4 important candidate genes (SPP1, BMP2, SMAD1 and IL1B) that were involved in osteoarthritis pathway." (PMID 29731966, 2018). "Therefore, SPP1, as a hub molecule connecting mechanical stress, inflammatory signals and ECM remodeling, plays a core role in the progression of osteoarthritis, but its precise mechanism requires additional validation through in vivo research." (PMID 41293726, 2025). "Moreover, we verified that SPP1 pathway enrichment scores increased, but VISFATIN pathway enrichment scores decreased based on the bulk rna-seq datasets in Osteoarthritis." (PMID 37082621, 2023).
kidney stone (48 papers, 2013 to 2026). "In previous studies, osteopontin (SPP1) was investigated in the urine of nephrolithiasis, Alzheimer’s disease patients, and in cancer patients presenting cisplatin-induced nephrotoxicity, and was found to provide diagnostic value." (PMID 35884419, 2022).
non-small cell lung carcinoma (48 papers, 2005 to 2026). A group of at least three distinct histological types of lung cancer, including non-small cell squamous cell carcinoma, adenocarcinoma, and large cell carcinoma. "For the first time, this study introduces the CXCL9/SPP1 polarity axis into the field of non-small cell lung cancer (NSCLC)." (PMID 42079623, 2026). "A number of previous studies have demonstrated correlations between levels of circulating SPP1 and/or increased SPP1 expression on tumor cells and poor prognosis in various cancers, including non-small cell lung cancer (NSCLC)." (PMID 37190178, 2023). "In the cell line level, non-small cell lung cancer ranked ninth among cancer cell lines based on SPP1 expression." (PMID 32595698, 2020). "Thus, in this study, we tried to accurately evaluate the SPP1 expression status on cancer cells and TAMs separately in patients with non-small cell lung cancer by using double immunohistochemistry." (PMID 36139536, 2022). "In non-small cell lung cancer (NSCLC), multiplex staining reveals enriched interactions between SPP1+ macrophages and FAP+ fibroblasts." (PMID 41425545, 2025). "SPP1 with glycolysis genes (GAPDH, ENO1, LDHA, ALDOA, and TPI1) was also expressed in TAMs in non-small cell lung cancer (NSCLC)." (PMID 38347955, 2023).
myocardial infarction (47 papers, 2011 to 2026). Gross necrosis of the myocardium, as a result of interruption of the blood supply to the area, as in coronary thrombosis. "Transcription of Spp1 (the gene encoding OPN) in cardiac macrophages peaked on day 3 after myocardial infarction and completely disappeared 28 days later." (PMID 34572084, 2021). "Our findings align with existing literature demonstrating the pro-fibrotic role of SPP1+ macrophages in other organ systems, particularly in myocardial infarction." (PMID 39691368, 2024). "In this study, we leveraged scRNA-seq data from a murine myocardial infarction time series to identify a profibrotic macrophage population defined by expression of Spp1 and elucidate the molecular cues that drive profibrotic macrophage differentiation." (PMID 36807143, 2023). "The IL-10–STAT3–galectin-3 axis was essential to generate SPP1 for reparative macrophage polarization after myocardial infarction, and these macrophages promoted tissue repair by promoting the clearance of fibrotic and apoptotic cells." (PMID 36569953, 2022). "SPP1 specifically appeared after myocardial infarction and was almost exclusively produced by galectin-3+CD206+ macrophages." (PMID 36569953, 2022). "High levels of intracellular galectin-3 expression are essential for the transcriptional activation of osteopontin [OPN; also known as secreted phosphoprotein 1 (Spp1)] in STAT3-mediated macrophage M2 polarization after myocardial infarction." (PMID 34307396, 2021). "SPP1 has also been shown to be expressed by macrophages during tissue repair after myocardial infarction, indicating its function in the tissue homeostasis function of macrophages as opposed to the inflammatory function." (PMID 33513762, 2021). "Finally, GEO database analysis showed that SPP1, as a biomarker for myocardial infarction (MI), participated in fibroblast proliferation and myocardial remodeling, and was also involved in the EMT mechanism." (PMID 41293726, 2025). "Similarly, spatial and single-cell analyses in human myocardial infarction tissue demonstrate accumulation of SPP1+ macrophages at infarct borders, where they closely interact with myofibroblasts to influence scar formation and remodeling." (PMID 40900730, 2025). "Meeting all the cutoff criteria across all the data set analyzed, MAN2A2/TNFRSF12A/SPP1/CSNK1D/PLAUR/PFKFB3/CXCL16 (herein we termed it MTSCPPC signature) was identified as a novel pathological signature of myocardial infarction and was used for subsequent analyses." (PMID 35163208, 2022). "SPP1 may play an important role in acute myocardial infarction after ischemia and reperfusion injury." (PMID 36158806, 2022). "In human myocardial infarction samples, about half of TREM2-expressing macrophages also co-express SPP1, indicating a shared phenotype involved in tissue repair and remodeling." (PMID 40520014, 2025). "Overall, the identified intercellular programmes aligned well with the existing literature on pro-fibrotic response upon myocardial infarction, including potential interactions of FN1 and SPP1 with ITGB1-containing complexes within ischaemic regions." (PMID 39223377, 2024). "The concentrations of SPP1 and CCL18 have been significantly and consistently upregulated within the local versus peripheral blood of acute myocardial infarction." (PMID 31449494, 2019). "After myocardial infarction, infiltrated macrophages are found in the myocardial infarction site, and the expression of SPP1, which is derived from macrophages, increases, but SPP1 is not expressed in normal cardiac tissue." (PMID 38919629, 2024).